KRAS (KRas proto-oncogene, GTPase)
Diseases named in the same sentence as KRAS in open-access papers (continued):
Sharing a sentence is not in itself a finding about the gene and the disease.
pancreatic cancer (continued). "Our study showed that gossypol treatment increased apoptotic death in pancreatic cancer cells by activating ER stress signaling via the upregulation of PERK and CHOP, regardless of the KRAS status." (PMID 35283426, 2022). "Moreover, oncogenic GTPase KRas (KRAS) induces NIX-mediated mitophagy and favors the development of pancreatic cancer, but the lack of NIX results in mitochondrial function restoration and thus delays the progression of pancreatic cancer." (PMID 40943612, 2025). "However, although PI3K-AKT signalling is reduced in KRAS G12R-mutant pancreatic cancer, it is not fully eradicated, and instead PI3K is thought to act independently to KRAS G12R, through activity of the γ subunit, rather than p110α." (PMID 39372214, 2024). "By activating MAPK dependent signaling pathway, KRAS leads to MYC up-regulation and transcription of nonoxidative pentose phosphate pathway (PPP) gene RPIA, thus promoting nucleotide biosynthesis and accelerating the development of pancreatic cancer." (PMID 38598912, 2024). "Despite that, several laboratories including ours suggest that the expression of PI3Kγ in tumor cells, albeit not strong, plays a critical role in KRASG12D,G12V pancreatic tumor cells, but also in KRASG12R pancreatic cells (a rarer form of mutant KRAS found in PDAC)." (PMID 36765741, 2023). "However, we chose to keep the same predictor tools, i.e., AllergenFP, that we had previously used for experimentally tested in-house data, including pancreatic cancer peptides (HRAS and KRAS) and non-structural COVID." (PMID 36298543, 2022). "From in vitro assays, we found that GPC1 committed to cellular proliferation or migration, that EVI1, KRAS and/or miR-96 regulated expression of GPC1, and that EVI1 modulated the oncogenic role of GPC1 in both pancreatic noncancerous cell lines and pancreatic cancer cell lines." (PMID 29245923, 2017). "While multiple reports have described the constitutively active oncogenic KRAS to be independent of EGFR, recent evidence in pancreatic cancer has indicated that signaling by mutant KRAS may be dependent on upstream activation proposed of EGFR." (PMID 25992771, 2015). "While preclinical efficacy from afatinib in pancreatic cancer has been suggested to correlate with EGFR/HER2/HER3 expression and occurred irrespective of KRAS status, disease stabilizations seen in KRASMUT tumors in our study may have been solely due to capecitabine chemotherapy." (PMID 40507311, 2025). "Although FOLFIRINOX does not directly target KRAS, this combination chemotherapy protocol which is primarily used to treat PDAC, also activates arginine metabolism, highlighting the role of metabolic reprogramming in the development of therapy resistance in pancreatic cancer." (PMID 40567499, 2025). "In addition, in one of them, the results indicated that this correlation is independent of KRAS status, but that there is an increase in expression of some proteins of the TMEJ pathway in pancreatic cancer cells, both in tumor samples and in cell lines carrying the activating KRAS mutation G12D." (PMID 39435280, 2024).
pancreatic cancer (continued). "Furthermore, some overexpressed enzymes upregulated by KRAS, such as RPIA, remain unchanged in some pancreatic cancer cell lines with KRAS deletion to maintain non-oxidative pentose phosphate pathway (PPP) and cancer cell survival via a KRAS-independent pathway." (PMID 37187730, 2023). "Our study showed that EPA treatment inhibited cell visibility and p-STAT3, HPS, and ACC-1, but not FASN expressions in KRAS-mutant SUIT-2 cells, suggesting that EPA treatment might reduce ACC-1-mediated de novo lipogenesis to downregulate the tumor growth and survival of pancreatic cancer cells." (PMID 33801246, 2021). "NRG1 fusions occur in ~ 3% NSCLC, ~ 1.5% pancreatic cancer and less than 1% of other cancers, and are detected frequently in KRAS–wildtype pancreatic ductal adenocarcinomas (PDAC) providing a potential drug target for those patients who do not benefit from KRAS inhibitors." (PMID 32989604, 2020).
lung adenocarcinoma (1,225 papers, 1998 to 2026). A carcinoma that arises from the lung and is characterized by the presence of malignant glandular epithelial cells. "A 58-year-old man with KRAS-G12C-mutated stage IVB lung adenocarcinoma initiated first-line treatment with carboplatin + pemetrexed + pembrolizumab." (PMID 41907597, 2026). "Molecular testing on the tumour showed that it harboured KRAS c.182A > T (p.Gln61Leu) mutation, which was similar to the mutation reported on the primary lung adenocarcinoma." (PMID 41716926, 2026). "Ranks as the third most frequently mutated gene in lung adenocarcinoma and demonstrates a significant co-mutation propensity with KRAS mutations, collectively defining the distinct biological KL (KRAS/STK11 co-mutant subtype)." (PMID 41541668, 2026). "A549 (STK11 deficient/KRAS mutant lung adenocarcinoma) cells again demonstrate increased glycolysis and increased HIF1α expression in normoxia, both of which are reduced with either STK11 re-expression or rapamycin treatment." (PMID 40069402, 2025). "This article reports a case of SCLC transformation occurring in a patient with KRAS-mutated lung adenocarcinoma after 16 months of ICIs combination therapy and provides a systematic review of 22 similar published cases." (PMID 40935646, 2025). "The other immune checkpoint inhibitor naïve NSCLC patient, who had PD on study treatment, had a KRAS/STK11-mutated PD-L1-negative lung adenocarcinoma." (PMID 41523436, 2025). "KRASG12C is the most common KRAS mutation in lung adenocarcinoma (LUAD), yet clinical responses to KRASG12C‐selective inhibitors (G12Ci) and immunotherapy remain variable." (PMID 41025426, 2025). "KRAS mutations, prevalent in 30% to 40% lung adenocarcinomas (LUAD) in Western populations, currently lack targeted first-line therapies." (PMID 40926995, 2025). "The KRAS G12D mutation is an activating alteration within the KRAS gene, a gene commonly mutated in several malignancies including lung adenocarcinoma." (PMID 39852181, 2025). "Approximately 25% of lung adenocarcinomas carry oncogenic mutations in the KRAS oncogene, leading to the activation of downstream survival pathways." (PMID 41002380, 2025). "All patients had lung adenocarcinoma with 13 patients (86%) having KRAS mutations (three G12C and 10 non-G12C)." (PMID 40486486, 2025). "This ratio is consistent with the previous findings on the epidemiology of NSCLC druggable mutations, where almost half of patients with lung adenocarcinoma had EGFR or KRAS mutations." (PMID 40075579, 2025). "We previously reported that KRAS-mutant/LKB1-deficient lung adenocarcinoma patients show altered AMPK-regulated gene circuits related to biological rhythms, which are controlled by the circadian clock." (PMID 40715535, 2025). "Patients with KRAS-mutant lung adenocarcinoma and co-mutations in STK11 and/or KEAP1 generally have the poorest prognosis." (PMID 40723270, 2025). "In East Asian populations, EGFR mutations are detected in up to 55% of lung adenocarcinomas, while KRAS mutations are less frequent." (PMID 40725263, 2025). "Kirsten Rat Sarcoma Viral Oncogene Homolog (KRAS) mutations are genetic drivers in numerous cancer types including lung adenocarcinoma (LUAD)." (PMID 40275403, 2025). "The most frequently mutated genes in lung adenocarcinomas are KRAS and Epidermal Growth Factor Receptor (EGFR), molecules in a common signaling pathway." (PMID 41002380, 2025).
lung adenocarcinoma (continued). "Deletion of the EZH2 allele accelerates lung adenocarcinoma progression in a kirsten rat sarcoma viral oncogene homolog (KRAS)-mutant mouse model, with downstream activation of AKT and ERK pathways promoting tumorigenesis." (PMID 40042761, 2025). "The KRAS oncogene is mutated in approximately 25% of lung adenocarcinomas and the RAS–RAF–MAPK pathway is frequently activated or dysregulated in NSCLC." (PMID 40486486, 2025). "KRAS mutations are present in approximately 20–30% of lung adenocarcinomas, are more prevalent in Western populations, and are strongly linked to smoking history." (PMID 40075579, 2025). "Loss of heterozygosity in KRAS is associated with improved prognosis for patients with early-stage lung adenocarcinoma." (PMID 40565600, 2025). "In patients with adenocarcinoma of the lung, compared with wild-type patients, patients with KRAS mutations are more likely to be diagnosed at an older age (>45 years) and have an increased rate of metastasis to the brain and liver." (PMID 41309533, 2025). "Approximately 30% of lung adenocarcinomas harbor KRAS mutations, with the G12C variant being the most prevalent, comprising about 40% of KRAS-altered NSCLC cases." (PMID 41373672, 2025). "The KRAS-G12C mutation, occurring in approximately 14% of lung adenocarcinomas, has emerged as a critical target for precision medicine strategies." (PMID 40316534, 2025). "Lung adenocarcinoma cells often develop mechanisms of resistance to ferroptosis, especially with KRAS mutation." (PMID 41155419, 2025). "KRAS (Kirsten rat sarcoma viral oncogene homolog) drives lung adenocarcinoma when mutations constitutively activate the RAS–MAPK pathway in distal lung epithelium." (PMID 41154602, 2025). "In 1817 KRAS-mutant lung adenocarcinomas, KEAP1 and SMARCA4 mutations correlated with metastasis and poor survival, while STK11’s impact varied by metastatic site and KEAP1 status." (PMID 40758706, 2025). "KRAS mutations are observed in 33% of lung adenocarcinomas, with KRAS G12C mutations accounting for 44% of these cases." (PMID 39996842, 2025). "Selected gene variants were confirmed in hereditary cancer syndrome with a higher risk of resistant KRAS mutated lung adenocarcinoma, colorectal and esophageal cancers, hepatocellular carcinoma, and glioblastoma." (PMID 40724954, 2025). "In this report, we describe a patient with advanced primary lung adenocarcinoma harboring a KRAS G12C mutation and high PD-L1 expression (TPS ≥50%) who underwent palliative brain radiotherapy followed by PD-1 antibody therapy." (PMID 41458605, 2025). "The KRAS-G12C mutation is present in approximately 14% of lung adenocarcinomas, establishing it as a critical target for precision medicine approaches." (PMID 40316534, 2025). "Background/Objectives: The clinical value of KRAS mutations in lung adenocarcinoma, alone or in combination with other mutations, has been assessed especially in advanced stages." (PMID 40725828, 2025). "In case of lung adenocarcinoma (LUAD) low proportion of IgA among all intratumoral Ig was associated with improved overall survival in a specific subset of patients with mutated KRAS gene." (PMID 40990023, 2025). "As STK11/LKB1 mutations occur in approximately one-third of KRAS-mutated lung adenocarcinomas, to uncover the potential mechanism is in high demand and is critical for developing effective combination strategies." (PMID 38291516, 2024). "PCAIs were previously tested on lung adenocarcinoma cell line A549 (derived from a White patient), which also carries a KRAS mutation." (PMID 39436906, 2024). "According to The Cancer Genome Atlas (TCGA), the three main KRAS mutations of lung adenocarcinoma are G12C (10–13%), G12V (5–6%) and G12D (4–5%)." (PMID 38994972, 2024). "For example, in lung adenocarcinoma cells that have mutated Ras, such as the KRAS mutation, macropinocytosis was found to be a major route of amino acid delivery." (PMID 38533500, 2024).
lung adenocarcinoma (continued). "Mutations in the KRAS (Kirsten rat sarcoma virus) gene occur in nearly a third of lung adenocarcinoma and have for decades been deemed an ‘undruggable’ target." (PMID 38846975, 2024). "Lung adenocarcinoma cells harboring KRAS mutations exhibit sensitivity to ferroptosis induced by SLC7A11 inhibitors." (PMID 38314086, 2024). "KRAS mutations are found in approximately 30% of lung adenocarcinomas in Europe and the US, and KRAS G12C mutations account for 41% of all KRAS mutations." (PMID 38466521, 2024). "We observed that PRSS1 and CTCF mutations in lung adenocarcinomas and skin melanomas show similar resistance-conferring effects to KRAS and NRAS mutations when treated with EGFR and BRAF inhibitors." (PMID 39160568, 2024). "The Kirsten rat sarcoma viral oncogene homolog (KRAS)G12C mutation is prevalent in lung adenocarcinoma (LUAD), driving tumor progression and indicating a poor prognosis." (PMID 38338834, 2024). "Here we determine the effects of PCAIs on the viability, G-protein levels, downstream mediators, and apoptosis-related proteins on the KRAS-mutated, Black American-derived lung adenocarcinoma cell line, NCI-H23." (PMID 39436906, 2024). "Glycine-12 mutations in the GTPase KRAS (KRASG12) are an initiating event for development of lung adenocarcinoma (LUAD)." (PMID 38755258, 2024). "Kirsten rat sarcoma viral oncogene homolog (KRAS) is the most frequently mutated oncogene in lung adenocarcinoma, the most common subtype of NSCLC." (PMID 39718828, 2024). "Active at all stages of tumor development, this pathway contributes significantly to cancer progression, especially through mutations like KRAS, which are found in 30% of lung adenocarcinomas." (PMID 39682234, 2024). "For example, in lung adenocarcinoma patients with KRAS mutations, applying treatments with MEK, ERK, or SHP2 inhibitors had better outcomes than standard treatment targeting EGFR38." (PMID 38783092, 2024). "The patient was a 62-year-old woman with lung adenocarcinoma harbouring a KRAS G12C mutation that was resistant to chemotherapy, including immune checkpoint inhibitors." (PMID 38269310, 2024). "This study focuses on the predictive value of pCASTOR1 in lung adenocarcinoma (LUAD) patients with KRAS mutations." (PMID 39385301, 2024). "In the present study, KRAS mutations were detected in 18% of patients with lung adenocarcinoma, but this rate is only approximately 10% among Japanese patients." (PMID 39037971, 2024). "STK11 encodes the tumor suppressor liver kinase B1 (LKB1), which suppresses tumor growth, and its mutation occurs in approximately 30% of KRAS-mutant lung adenocarcinoma cases; this mutation can promote KRAS-driven cancer growth and early metastasis." (PMID 39037971, 2024). "For example, in KRAS-mutated lung adenocarcinoma cells, the secretion of proinflammatory cytokines, including interleukin-6, activates JAK1 and JAK2 through glycoprotein 130 in an autocrine loop, thus, contributing to malignant progression." (PMID 38706597, 2024). "Specifically, KRAS mutations are involved in the three most lethal cancers in the U.S., namely pancreatic ductal adenocarcinoma, colorectal adenocarcinoma, and lung adenocarcinoma." (PMID 38473821, 2024).